NIP7 (nucleolar pre-rRNA processing protein NIP7)
Description:
Required for proper 34S pre-rRNA processing and 60S ribosome subunit assembly.
Synonyms: CGI-37; HSPC031; FLJ10296; KD93
Tractability: Small molecule: a structure with a bound ligand is known. PROTAC: ubiquitination databases record sites on it; its protein half-life has been measured.
Gene: Protein-coding gene on chromosome 16 (69,337,996 to 69,343,106, forward strand). Ensembl gene ENSG00000132603.
Subcellular location: Nucleus, nucleolus
Subcellular location (Human Protein Atlas): Nucleoli; Cytosol; Nucleoplasm
Pathways (Reactome):
Metabolism of RNA: Major pathway of rRNA processing in the nucleolus and cytosol
Gene Ontology:
Molecular function: protein binding; RNA binding
Biological process: ribosomal large subunit biogenesis; ribosome assembly
Cellular component: nucleolus; preribosome, large subunit precursor; nucleus
Genetic constraint (gnomAD): Loss-of-function variants: 12 observed, 21.37 expected, observed/expected ratio (o/e) 0.56, 90% interval 0.36 to 0.91. The upper end of that interval is the gene's LOEUF score, 0.91, which puts it in group 3 of 6, group 1 being the genes least tolerant of losing a copy. Missense variants: 226 observed, 239.92 expected, observed/expected ratio (o/e) 0.94, 90% interval 0.84 to 1.05. Synonymous variants: 103 observed, 93.57 expected, observed/expected ratio (o/e) 1.1, 90% interval 0.94 to 1.3.
Homologues: Orthologues: chimpanzee NIP7 (100% identical), macaque NIP7 (99% identical), pig NIP7 (98% identical), mouse Nip7 (98% identical), rat Nip7 (97% identical), guinea pig NIP7 (97% identical), dog NIP7 (96% identical), tropical clawed frog nip7 (84% identical), zebrafish nip7 (82% identical), Drosophila melanogaster CG7006 (65% identical), Caenorhabditis elegans C43E11.9 (61% identical). Paralogues in human: CKS1B (14% identical), CKS2 (14% identical).
Diseases named in the same sentence as NIP7 in open-access papers:
NIP7 is named in the same sentence as 6 diseases in open-access papers, as found by Europe PMC text mining. Sharing a sentence is not in itself a finding about the gene and the disease. The quoted sentences say what the papers report.
lung cancer (3 papers, 2022 to 2024). A malignant neoplasm involving the lung. "Notably, certain genes, such as CTLA4, MZB1, NIP7, and BUB1B in ADC, as well as GNG11 and CCNB2 in SCC, were found to be associated with tumor size, adding a crucial dimension to our understanding of lung cancer biology." (PMID 38612418, 2024).
liposarcoma (2 papers, 2019 to 2021). A usually painless malignant tumor that arises from adipose tissue. "In liposarcoma, NIP7, RPL10L, and MCM2 are significantly associated with long-term no recurrence survival rate." (PMID 34712323, 2021). "Interestingly, NIP7 has been also identified as the gene among in a three-gene signature significantly associated with RFS in liposarcoma." (PMID 31877723, 2019).
glioblastoma (1 paper, 2022). The most malignant astrocytic tumor (WHO grade IV). "NIP7 was significantly upregulated in the TCGA glioblastoma dataset." (PMID 35270630, 2022).
tumor (2 papers, 2019 to 2024). "CTLA4, MZB1, NIP7, and BUB1B in ADC, as well as GNG11 and CCNB2 in SCC, are novel top hub genes in modules associated with tumour size, SUVmax, and recurrence-free survival." (PMID 31877723, 2019).
infection (1 paper, 2022). The state of being infected such as from the introduction of a foreign agent such as serum, vaccine, antigenic substance or organism. "In contrast, almost 100 transcripts related to genes typically involved in viral protein translation during infection (e.g. rps2, 12, 14; wdr12; rpf2; nip7; eif4; eif4ebp3l; eif4a3; eif4ea; eif4b) were down-regulated." (PMID 35710351, 2022).
NIP7 also shares sentences with these, for which no sentence is quoted: melanoma (1 paper).